C2CD2L (C2CD2 like)
Description:
Lipid-binding protein that transports phosphatidylinositol, the precursor of phosphatidylinositol 4,5-bisphosphate (PI(4,5)P2), from its site of synthesis in the endoplasmic reticulum to the cell membrane. It thereby maintains the pool of cell membrane phosphoinositides, which are degraded during phospholipase C (PLC) signaling. Plays a key role in the coordination of Ca(2+) and phosphoinositide signaling: localizes to sites of contact between the endoplasmic reticulum and the cell membrane, where it tethers the two bilayers. In response to elevation of cytosolic Ca(2+), it is phosphorylated at its C-terminus and dissociates from the cell membrane, abolishing phosphatidylinositol transport to the cell membrane. Positively regulates insulin secretion in response to glucose: phosphatidylinositol transfer to the cell membrane allows replenishment of PI(4,5)P2 pools and calcium channel opening, priming a new population of insulin granules.
Synonyms: KIAA0285; TMEM24; DLNB23
Tractability: Antibody: UniProt places it where antibodies can reach, with high confidence; its Gene Ontology location is reachable by antibodies, with high confidence; UniProt predicts a signal peptide or a membrane-spanning region; the Human Protein Atlas places it where antibodies can reach. PROTAC: ubiquitination databases record sites on it; its protein half-life has been measured.
Gene: Protein-coding gene on chromosome 11 (119,102,198 to 119,118,544, forward strand). Ensembl gene ENSG00000172375.
Subcellular location: Endoplasmic reticulum membrane; Cell membrane
Subcellular location (Human Protein Atlas): Plasma membrane
Gene Ontology:
Molecular function: phosphatidylinositol binding; phosphatidylinositol transfer activity; protein binding; insulin binding
Biological process: positive regulation of insulin secretion involved in cellular response to glucose stimulus; intermembrane lipid transfer
Cellular component: cortical endoplasmic reticulum; cytoplasmic side of apical plasma membrane; endoplasmic reticulum membrane; endoplasmic reticulum-plasma membrane contact site; plasma membrane; membrane
Genetic constraint (gnomAD): Loss-of-function variants: 22 observed, 63.62 expected, observed/expected ratio (o/e) 0.35, 90% interval 0.25 to 0.49. The upper end of that interval is the gene's LOEUF score, 0.49, which puts it in group 2 of 6, group 1 being the genes least tolerant of losing a copy. Missense variants: 803 observed, 931.08 expected, observed/expected ratio (o/e) 0.86, 90% interval 0.81 to 0.91. Synonymous variants: 363 observed, 385.81 expected, observed/expected ratio (o/e) 0.94, 90% interval 0.86 to 1.03.
Homologues: Orthologues: macaque C2CD2L (98% identical), chimpanzee C2CD2L (97% identical), rabbit C2CD2L (94% identical), dog C2CD2L (93% identical), guinea pig C2CD2L (93% identical), pig C2CD2L (92% identical), rat C2cd2l (91% identical), mouse C2cd2l (91% identical), zebrafish c2cd2l (51% identical), tropical clawed frog c2cd2l (48% identical), Caenorhabditis elegans tmem-24 (19% identical), Drosophila melanogaster CG10737 (17% identical). Paralogues in human: C2CD2 (29% identical).
Diseases named in the same sentence as C2CD2L in open-access papers:
C2CD2L is named in the same sentence as 4 diseases in open-access papers, as found by Europe PMC text mining. Sharing a sentence is not in itself a finding about the gene and the disease. The quoted sentences say what the papers report.
insomnia (1 paper, 2023). A sleep disorder characterized by difficulty in falling asleep and/or remaining asleep. "In summary, we identified a key gene (C2CD2L) that may facilitate the development of biomarkers for insomnia." (PMID 38090272, 2023).
C2CD2L also shares sentences with these, for which no sentence is quoted: neuroblastoma (2 papers); breast carcinoma (1); melanoma (1).